SNAP47 (synaptosome associated protein 47)
Description:
Plays a role in intracellular membrane fusion.
Synonyms: SNAP-47; C1orf142; HEL170; SVAP1; ESFI5812; HEL-S-290
Tractability: Antibody: its Gene Ontology location is reachable by antibodies, with medium confidence. PROTAC: ubiquitination databases record sites on it; its protein half-life has been measured.
Gene: Protein-coding gene on chromosome 1 (227,728,200 to 227,781,826, forward strand). Ensembl gene ENSG00000143740.
Subcellular location: Endomembrane system; Cytoplasm, perinuclear region
Subcellular location (Human Protein Atlas): Cytosol
Gene Ontology:
Molecular function: protein binding; SNAP receptor activity; syntaxin binding
Biological process: cellular response to starvation; exocytosis; macroautophagy; synaptic vesicle fusion to presynaptic active zone membrane; synaptic vesicle priming; vesicle fusion
Cellular component: BLOC-1 complex; SNARE complex; autophagosome membrane; lysosomal membrane; endomembrane system; perinuclear region of cytoplasm; presynapse; synapse
Genetic constraint (gnomAD): Loss-of-function variants: 20 observed, 35.18 expected, observed/expected ratio (o/e) 0.57, 90% interval 0.4 to 0.83. The upper end of that interval is the gene's LOEUF score, 0.83, which puts it in group 3 of 6, group 1 being the genes least tolerant of losing a copy. Missense variants: 492 observed, 556.25 expected, observed/expected ratio (o/e) 0.88, 90% interval 0.82 to 0.95. Synonymous variants: 194 observed, 224.79 expected, observed/expected ratio (o/e) 0.86, 90% interval 0.77 to 0.97.
Homologues: Orthologues: chimpanzee SNAP47 (99% identical), macaque SNAP47 (86% identical), rabbit SNAP47 (75% identical), pig SNAP47 (74% identical), rat Snap47 (73% identical), dog SNAP47 (68% identical), mouse Snap47 (67% identical), guinea pig SNAP47 (64% identical), zebrafish snap47 (48% identical), tropical clawed frog snap47 (42% identical). Paralogues in human: SNAP29 (14% identical), SNAP23 (12% identical), SNAP25 (11% identical).
Diseases named in the same sentence as SNAP47 in open-access papers:
SNAP47 is named in the same sentence as 38 diseases in open-access papers, as found by Europe PMC text mining. Sharing a sentence is not in itself a finding about the gene and the disease. The quoted sentences say what the papers report.
Obesity (4 papers, 2017 to 2025). Accumulation of substantial excess body fat. "It is ubiquitously expressed, and recent evidence also support a role for SNAP47 in regulation of autophagic flux, which represent a potential link to obesity." (PMID 41225618, 2025). "SNAP47 and PPP1R9A are associated with neuronal pathways and have to our knowledge not yet been studied in the context of obesity." (PMID 41225618, 2025).
lung carcinoma (3 papers, 2021 to 2023). "After stromal deprivation, the lymphocyte spectrum specific Ets transcription factor SPIB was activated and directly enhanced SNAP47 transcription in certain lung cancer cells." (PMID 38049825, 2023). "Activated SPIB directly enhanced SNAP47 transcription in lung cancer cells and increased anoikis resistance." (PMID 36230714, 2022). "Activated transcription factor Spi-B (SPIB) enhances SNAP47 transcription and mitigates anoikis in lung cancer." (PMID 36230714, 2022).
heart failure (1 paper, 2020). Inability of the heart to pump blood at an adequate rate to meet tissue metabolic requirements. "Recent work examining tissue from the RV of human heart failure patients found a set of genes that are unique to RV failure compared to LV failure: WIPI1, HSPB6, SNAP47 and MAP4." (PMID 31960631, 2020).
viral infection (1 paper, 2021). "Relative to the sham-infected cells, LC3-II showed an expected increase in both WT and SNAP47-KO cells after 8 hours of viral infection." (PMID 34440910, 2021). "we showed that protein levels of SNAP47 are reduced upon CVB3 infection and that the knockdown of SNAP47 suppresses viral infection." (PMID 34440910, 2021).
infection (1 paper, 2021). The state of being infected such as from the introduction of a foreign agent such as serum, vaccine, antigenic substance or organism. "In contrast, SNAP47 was downregulated, starting at ~5 h post-infection." (PMID 34440910, 2021).
tumor (1 paper, 2016). "By analyzing the Human Protein Atlas, we compared the protein expression of SNAP23, SNAP25, SNAP29 and SNAP47 in ovarian normal and tumor tissues." (PMID 27855700, 2016).
SNAP47 also shares sentences with these, for which no sentence is quoted: cancer (3 papers); diabetes (3); liver cirrhosis (3); gastric cancer (2); Hyperglycemia (2); inflammatory bowel disease (2); liver fibrosis (2); non-alcoholic fatty liver disease (2); aortic stenosis (1); atherosclerosis (1); autism (1); brain disorder (1); cardiovascular diseases (1); chronic heart failure (1); Cirrhosis (1); Cognitive impairment (1); colorectal cancer (1); Constipation (1); coronary artery disease (1); endothelial dysfunction (1); hepatocellular carcinoma (1); Hypertension (1); hypovitaminosis D (1); Insulin resistance (1); liver disease (1); lymph node metastasis (1); multiple sclerosis (1); Parkinson disease (1); prediabetes (1); pregnancy induced hypertension (1).
A further 2 diseases each share a sentence with SNAP47 in 1 paper.